PIK3CA (phosphatidylinositol-4,5-bisphosphate 3-kinase catalytic subunit alpha)
Diseases named in the same sentence as PIK3CA in open-access papers (continued):
Sharing a sentence is not in itself a finding about the gene and the disease.
cancer (continued). "These mutations are found throughout the PIK3CA gene but are highly enriched at hotspot amino acid sites in the helical (E542K, E545K) and kinase (H1047R/L) domains, though the frequency of PI3Kα hotspot mutations varies across cancers." (PMID 37623743, 2023). "Here, one-third of the sequenced cancers showed a PIK3CA hotspot mutation." (PMID 37178424, 2023). "However, the p110α subunit mutation in PIK3CA is considered one of the most prevalent mutations involved in cancer development." (PMID 37489050, 2023). "In detail, PIK3CA mutations are described in >10% of cancer patients and have been recognized as pathogenetic in many solid tumors such as breast, endometrial, bladder, colorectal, and head and neck squamous cell carcinoma, as well as in other benign skin lesions (e.g., epidermal nevi)." (PMID 38136956, 2023). "Gedatolisib is a drug under development used in cancer patients with mutations in PIK3CA." (PMID 37368773, 2023). "Our study confirms the very wide variety of PIK3CA mutations identified in cancer." (PMID 36934165, 2023). "The activation of mutations in PIK3CA is reported to play a role in many human cancers." (PMID 37667289, 2023). "We expected PIK3CA mutations to occur at a higher frequency in malignant tumors." (PMID 38033642, 2023). "Interestingly, PIK3CA showed the highest frequency of mutations among all ARGs in different cancers, which was consistent with previous studies." (PMID 36937870, 2023). "The results presented here are original because they describe the prevalence of PIK3CA mutations, not only in hotspots, but also outside mutational hotspots, in a large, pan-cancer cohort representative of the real-life clinical activity of a cancer center." (PMID 36934165, 2023). "A recent trial of the mTOR inhibitor, everolimus, in combination with cisplatin given preoperatively to TNBC patients with residual disease following preoperative anthracycline/taxane showed responses to therapy in patients whose cancers had a PIK3CA mutation or a germline PALB2 mutation." (PMID 37491309, 2023). "Among the 34 ARGs, PIK3CA showed the highest mutation frequency in different cancer types." (PMID 36937870, 2023). "Inavolisib is a recently developed, orally administered, strong p110α inhibitor, which induces a specific degradation of the mutated form of PIK3CA, as already described with taselisib, associated with an exquisite activity in PIK3CA-mutated cancer preclinical models." (PMID 36900211, 2023). "As our series included many cases of metastatic breast cancer, we also carried out exploratory analysis of the association between PIK3CA mutations and response to different types of anti-cancer treatments, such as chemotherapy and pharmacological agents targeting the PI3K-AKT-mTOR pathway." (PMID 36934165, 2023). "Molecular analysis revealed that the patient carried the PIK3CA H1047R cancer mutation and the POLE F699fs*11 mutation that is associated with high TMB and may benefit from immune checkpoint inhibition." (PMID 37187745, 2023). "Regarding the mortality of LMs, because they are associated with mutations in the PIK3CA gene, and the PIK3CA gene is associated with several cancers, patients with LMs may be more likely to develop cancer." (PMID 37626114, 2023). "Other reports found an association of PIK3CA mutations with positive lymph node status suggesting that activation of the PI3K/Akt pathway may increase the invasion of cancer cells into the lymph nodes." (PMID 37195967, 2023).
cancer (continued). "GOF point mutations in the PIK3CA gene have been identified as causative oncogenic mutations in various cancer types, particularly in reproductive cancers, making PIK3CA one of the major cancer driver genes." (PMID 37109059, 2023). "The seven prevalent ‘candidate genes’ (ADAM10, ADAM17, AKT1, CTNNB1, ESR1, FGFR1, PIK3CA) showed direct associations with enriched terms under the categories of ‘Neurodegenerative disorders’, ‘Neurodevelopmental diseases’, ‘CNS tumour/cancer’ and ‘Cellular Signaling pathways’." (PMID 36229517, 2022). "Herein, we analyzed the epidemiologic landscape of PIK3CA mutations in a cohort of 11,904 Chinese pan-cancer samples and identified the unique mutation features of PIK3CA gene in the Chinese population based on comparative studies between the Chinese and Western cohorts." (PMID 35778737, 2022). "PIK3CA, encoding p110α, is frequently mutated in human cancers." (PMID 35418124, 2022). "As reported in the SOLAR‐1 trial, whether PIK3CA mutation is detected in plasma ctDNA or in cancer tissue, patients can benefit remarkably from alpelisib and fulvestrant combination therapy." (PMID 38089455, 2022). "We analyzed PIK3CA mutation status in sequencing data of cell-free DNA from plasma and genomic DNA from matched peripheral blood lymphocyte in 11,904 Chinese pan-cancer patients, and compared them with genomic data from the Catalogue of Somatic Mutations in Cancer (COSMIC) database." (PMID 35778737, 2022). "PIK3CA is the most frequently mutated oncogene in all cancers." (PMID 35740668, 2022). "Statistical analyses on the frequencies of mutation hotspots and CNVs in PIK3CA among different cancers types revealed that the CNV was most commonly detected in SCL and LUSC, while E545K, E542K and H1047R were the most frequently identified mutations in most cancers." (PMID 35778737, 2022). "To test this hypothesis, we determined the cancer cell fraction (CCF), a measurement of mutation clonality, in a pan-cancer cohort of n = 131 patient samples harboring PIK3CA (H1047L)." (PMID 35484264, 2022). "The largest APOBEC-related cancer effects are attributable to mutations in PIK3CA and NFE2L2." (PMID 35872531, 2022). "Some pan-cancer hotspot mutations, such as PIK3CA E545K (6.93%), could be recognized by at least one HLA molecule." (PMID 35387130, 2022). "The PIK3CA mutation testing can be performed with either cancer tissue or plasma ctDNA specimens." (PMID 38089455, 2022). "PIK3CA is a commonly mutated cancer-associated gene, making it an attractive therapeutic target." (PMID 36385120, 2022). "All of these studies reported concordant mutations in PIK3CA either in cancer or in contiguous AE." (PMID 35457244, 2022). "De novo variants in significantly mutated regions (SMRs) genes (PIK3CA, C6, and PPP2R2B) were over-represented in CC patients, especially PIK3CA with excess mutations implicated in 9 cancer types, indicating that it may play a role in malignancy." (PMID 35741793, 2022). "We analyzed circulating cell-free DNA (cfDNA) extracted from plasma using high-depth massively parallel sequencing targeting 468 cancer-associated genes, and we identified a clonal hotspot missense mutation in the PIK3CA gene (3:178952085, A > G, H1047R) and amplification of the CCND1 gene." (PMID 36551247, 2022). "One of those include PIK3CA gene, which is one of the most common mutations in cancer of all types." (PMID 35225964, 2022). "This cancer may be caused by microsatellite instability and mutations in PIK3CA, PTEN, CTNNBI.3, and K-RAS genes." (PMID 35250573, 2022).
cancer (continued). "Previous reports have revealed that mutations in the helix domain and kinase domain of PIK3CA cause activation through different mechanisms, and the mutation process may be related to driving mutations in a variety of cancers." (PMID 35575002, 2022). "Besides, concomitant genomic aberrations in PIK3CA-mutated samples were detected to investigate cancer driver genes, as well as their enriched pathways." (PMID 35778737, 2022). "Research on EGFR-mutant cancer cell lines revealed that gefitinib resistance was associated with an oncogenic mutation in phosphatidylinositol-4,5-bisphosphate 3-kinase catalytic subunit alpha (PIK3CA)." (PMID 35814435, 2022). "Indeed, Py-Im can also be used to target cancer-specific coding region, such as the gene body of cancer-driving mutant E545K in PIK3CA, a hotspot mutation that occurs in 23 to 36% of cervical cancer cases." (PMID 35022237, 2022). "Because PIK3CA gain-of-function mutations are critical to cancer cell fitness, we hypothesized that Mut PIK3CA would be clonally conserved across patients and disease sites." (PMID 35484264, 2022). "The presence of the H1047R mutation in PIK3CA, a well-established oncogenic driver, in the third patient, suggests that the PI 3-kinase pathway is also activated in this patient, likely making it a multi-driver cancer." (PMID 36011019, 2022). "The p110α subunit of PIK3CA is frequently mutated and amplified (~30%) in a variety of cancers." (PMID 33801659, 2021). "Also, it implies the need for research of novel treatment strategies, such as the tyrosine kinase inhibitors (TKIs) targeting angiogenic kinases, mTOR-inhibitors in PIK3CA mutated cancers, or immunotherapy with checkpoint inhibitors in PD-L1 positive cancers." (PMID 34394349, 2021). "PIK3CA, the gene encoding for the alpha catalytic subunit of phosphatidylinositol-4,5-bisphosphate 3-kinase, is one of the most frequently mutated oncogenes in cancer." (PMID 33435133, 2021). "PIK3CA represents the most frequently mutated gene in these cancers." (PMID 33435133, 2021). "Accordingly, our study aimed to investigate the functional behavior of these KRAS and PIK3CA cancer-driver genes along with identifying the somatic mutations associated with the aggressive benign tumor in the developed immortalized endometriotic epithelial cell line, HMOsisEC10." (PMID 34202354, 2021). "PIK3CA is indeed most frequently mutated in breast cancer (28.8%), principally in estrogen receptor (ER)-positive carcinomas (38.9%), as well as endometrium (27.4%) and urinary tract (20.2%) cancers." (PMID 34944785, 2021). "PIK3CA mutation is one of the most common mutations in human cancer." (PMID 34976987, 2021). "However, a similar case of early-onset cancer in combination with a mosaic PIK3CA variant is reported in the gnomAD-TCGA database, supporting the increased cancer risk associated with mosaicism for this variant." (PMID 34075207, 2021). "MMR and proofreading polymerases mutations are more often seen in PIK3CA mutated cancers." (PMID 33435133, 2021).
cancer (continued). "Activating mutations in PIK3CA transcripts were detected in two different primary cancer samples, one containing a variant (PIK3CA E545K) at high mutant allele fraction variant and another cancer containing a different variant (PIK3CA H1047R) at a lower allele fraction." (PMID 33541297, 2021). "PIK3CA mutations are the most frequent among all isoforms in cancer." (PMID 34769309, 2021). "PIK3CA mutations have been found to be involved in TKI resistance in several cancer models." (PMID 34249687, 2021). "PIK3CA is an oncogene whose mutated form exhibits increased kinase activity, causing cancer cell proliferation and the relative high mutation of this gene in DGC may reflect the specificity of mutations in this gene to DGC." (PMID 34804623, 2021). "PIK3CA gene was activated missense mutation and cancer hotspots were E542K, and H1047R." (PMID 34409758, 2021). "In cancer, there are four common genetic events that drive cancer progression which include 1) PIK3CA activating mutations, 2) PTEN loss-of-function mutations and deletions, 3) gain-of-function mutations in Akt-encoding genes, and lastly 4) amplification of RTKs that activate PI3K signaling." (PMID 34867402, 2021). "Here, by investigating a panel of cancer-associated genes in a Danish population, our data showed that patients were further stratified into four different molecular subgroups: “PIK3CA”, “ARID1A”, “PIK3CA-ARID1A” and “Undetermined”, in regard to the presence of mutation on these genes." (PMID 34680390, 2021). "ARID1A mutation in cancer was found to occur synergistically with PIK3CA." (PMID 34217266, 2021). "The PIK3CA gene encoding p110α catalytic subunit of PI3K is often mutated in most of cancer types." (PMID 34830339, 2021). "Generally, PIK3CA is the most common mutation location in cancer patients." (PMID 34217313, 2021). "Moreover, cancer cells that have an active mutation on the PIK3CA gene and/or present a high microsatellite instability (MSI-high) seem to demonstrate a higher sensitivity to active lactam steroidal alkylators." (PMID 34440232, 2021). "There are three class IA p110 isoforms (α, β, δ) expressed by the genes phosphatidylinositol-4,5-bisphosphate 3-kinase catalytic subunit alpha (PIK3CA), PIK3CB and PIK3CD, respectively, of which PIK3CA is the most frequently mutated in multiple cancer types, including EOC." (PMID 35582310, 2021). "Silencing FSCN1 enhances radiosensitivity and promotes apoptosis in cancer cells with PIK3CA alterations, and this process may be associated with the downregulation of YWHAZ." (PMID 34249689, 2021). "PIK3CA, which encodes p110α, is frequently mutated in cancer as an important drug target." (PMID 34607583, 2021). "PIK3CAH1047R is the most common activating PIK3CA mutation in human cancers and in PROS." (PMID 33514588, 2021). "PIK3CA is the second most frequently mutated oncogene across cancers." (PMID 33435133, 2021). "Such situations may arise during the development of HPV(+) cancers that have mutations in PIK3CA (or downstream effectors) and/or become refractory to EGFR or PI3K inhibitors, which we and others reported can lead to MEK/ERK stimulation via other RTKs." (PMID 33481911, 2021). "Therefore, PIK3CA mutations need to be investigated further as a potential therapeutic target in cancers." (PMID 32704014, 2020). "We therefore speculated that aspirin treatment might be useful for cancers that require glutamine for progression such as PIK3CA-mutated CRC, although preclinical and clinical studies are needed." (PMID 32365457, 2020). "Of these, PIK3CA is the most frequently mutated in human cancer." (PMID 32604863, 2020).
cancer (continued). "Although several studies have now demonstrated that the presence of PIK3CA mutations modifies the effect of cancer therapies such as trastuzamab and letrozole, the effect of other medications, including aspirin and other non-steroidal anti-inflammatory drugs (NSAIDS), remains understudied." (PMID 32326897, 2020). "PIK3CA is one of the most common oncogenic mutations in cancer." (PMID 32350708, 2020). "The PIK3CA mutation prevalence rate in each cancer type varied." (PMID 33166334, 2020). "The cancer driver PIK3CA was frequently mutated in all three cancer types (122/209, 58%)." (PMID 33194730, 2020). "Postzygotic variants of PIK3CA are associated with diverse cancers, especially breast cancers." (PMID 32778138, 2020). "PIK3CA was reported to have association with drug sensitivity in many cancer types including ESCC." (PMID 32617189, 2020). "Both the RAS activation pathway and PIK3CA mutations are key, common cancer genomic alterations." (PMID 33166334, 2020). "The role of this variant in OC and other cancer susceptibility may be due to diverse role of PIK3CA in the initiation and progression of OC." (PMID 33273524, 2020). "PIK3CA is the second most commonly mutated gene in all cancers and accounts for 52.2% of ECs." (PMID 33381450, 2020). "Moreover, 38 PIK3CA-mutant tumors with pMMR were also tested by the hybrid capture-based NGS testing to determine the somatic mutations of 33 cancer-related genes and MSI status." (PMID 32328187, 2020). "The median prevalence rate of PIK3CA mutation for each cancer type was 0.03 (range 0–0.33)." (PMID 33166334, 2020). "There is evidence that even major and/or cancer-initiating driver mutations (e.g. APC, IDH1/2, KRAS, PIK3CA, etc.)are differentially selected depending on cancer type, strongly suggesting a role for the TME, broadly defined, in selecting many of the common driver mutations." (PMID 32289242, 2020). "Several reports on various cancers indicated mutual exclusivity between PIK3CA mutations and PIK3CA amplification, suggesting that each of these alterations may individually be sufficient to drive their carcinogenesis independently 20,21." (PMID 32410843, 2020). "Our model showed good performance in predicting PIK3CA mutations in various cancer types." (PMID 33166334, 2020). "Besides, alterations in other gene mutations were also associated with glycolysis in other cancer types, for example, higher PIK3CA mutation event was found in glycolysis-high group of COAD (adj." (PMID 32635458, 2020). "However, a review of the literature highlights recent mutational analyses that show important differences between these two cancer types, including an increase in PIK3CA mutations in primary SCCB." (PMID 32411090, 2020). "PIK3CA-mutated cancers have been shown to be sensitive to PI3K inhibitors." (PMID 32641355, 2020). "The carcinomas had more than five times more CNVs than other devil cancers, and each harboured high copy number amplicons carrying known cancer genes (PIK3CA and MYCL, respectively), confirming that CNV mutation burden and cancer gene involvement vary across devil cancer histotypes." (PMID 33232318, 2020). "A plethora of literature points to the association between these mutations and resistance to common therapies especially anti-EGFR treatment as well as cancer progression, highlighting the need to detect PIK3CA p110α mutation as a strong predictive and prognostic biomarker." (PMID 32099598, 2019).